CDK5 (cyclin dependent kinase 5)
Diseases named in the same sentence as CDK5 in open-access papers (continued):
Sharing a sentence is not in itself a finding about the gene and the disease.
pituitary adenomas (5 papers, 2014 to 2023). "Previously we reported that cyclin-dependent kinase 5 (CDK5) is upregulated in pituitary tumors associated with activating protein p35, and plays an essential role in pituitary adenomas progression." (PMID 27438154, 2016). "In our previous study, we found that active CDK5 was present in normal pituitary cells, associated with p35, and that CDK5 activity was upregulated in pituitary adenomas." (PMID 27438154, 2016). "Previously, we have found that active CDK5 was present in normal human pituitary tissue, was associated with p35, and that CDK5 activity was upregulated in diverse types of pituitary adenomas, suggesting CDK5 activity may play a role in pituitary tumor progression." (PMID 27438154, 2016). "CDK5 expression and activity are significantly higher in invasive pituitary adenomas than in noninvasive pituitary adenomas." (PMID 37993880, 2023). "CDK5 also enhances the migration and invasion of prolactin pituitary adenomas, predominantly by phosphorylation of kinase insert domain receptor (KDR, also known as VEGFR2) at S229." (PMID 37993880, 2023). "In summary, our results illustrated that CDK5-mediated KDR phosphorylation controls prolactin pituitary adenoma progression and KDR pSer-229 serves as a potential prognostic biomarker for both noninvasive and invasive pituitary adenomas." (PMID 27438154, 2016). "Immunoprecipitation of KDR led to coprecipitation of a detectable amount of CDK5 in noninvasive pituitary adenomas, with more intensive signaling in invasive pituitary adenomas." (PMID 27438154, 2016). "To further examine CDK5 activity, we analyzed the phosphorylation levels of CDK5 in human prolactin pituitary adenomas." (PMID 27438154, 2016). "Expression of p-CDK5 was significantly higher in invasive (mean H-score: 266) than in noninvasive prolactin pituitary adenomas (mean H-score: 194)." (PMID 27438154, 2016). "To determine the influence of CDK5 on the migration and invasion of prolactin pituitary adenomas, we incubated GH3 rat pituitary cells with either treatments of roscovitine (a CDK5 inhibitor) in different concentrations." (PMID 27438154, 2016). "The functional role of CDK5 activity in cell proliferation, migration, and invasiveness of pituitary adenoma cells remains to be elucidated." (PMID 27438154, 2016). "Here, we have demonstrated that CDK5 phosphorylates KDR at Ser-229 in prolactin pituitary adenomas, a step that is required for normal cell surface expression of KDR in cell migration and invasion in vitro." (PMID 27438154, 2016). "Our data indicate that p35 expression and CDK5 activity are both significantly increased in human invasive prolactin pituitary adenomas as compared to noninvasive forms of pituitary adenomas." (PMID 27438154, 2016). "We have found both p35 and p-CDK5 levels are significantly increased in invasive pituitary adenomas in comparison to noninvasive pituitary adenomas." (PMID 27438154, 2016). "In the current study, we have sought to explore the biological functions of CDK5 and p35 in prolactin pituitary adenomas." (PMID 27438154, 2016). "In addition, our findings showed that CDK5 inhibitors can directly or indirectly block cell migration and invasion in prolactin pituitary adenomas." (PMID 27438154, 2016). "Here we explored the mechanisms of CDK5 signaling in prolactin pituitary adenomas." (PMID 27438154, 2016). "The CDK5 mechanisms involved in other subtypes of pituitary adenoma will be studied in the future." (PMID 27438154, 2016). "First, we asked whether the expression of CDK5 or p35 differs in invasive and noninvasive prolactin pituitary adenomas." (PMID 27438154, 2016). "The data suggest that CDK5 might also regulate DA resistance and tumor growth in prolactin pituitary adenomas." (PMID 27438154, 2016). "It has been shown that increased CDK5-mediated VEGF expression might play a crucial role in the development of pituitary adenomas." (PMID 25505910, 2014).
pituitary adenomas (continued). "Our results indicate that CDK5 mediates cell invasion through phosphorylation on KDR Ser-229 and KDR pSer-229 is a potential biomarker for pituitary adenomas." (PMID 27438154, 2016). "To determine whether there is a direct interaction between CDK5 and KDR, we immunoprecipitated KDR from human pituitary adenoma lysates and probed with a CDK5-specific antibody." (PMID 27438154, 2016).
chronic lymphocytic leukemia (4 papers, 2017 to 2025). "By immunoblotting, we observed that CDK5 and its activator p35 are overexpressed in a panel of lymphoma cell lines, including DLBCL, Hodgkin lymphoma, Burkitt lymphoma, and chronic lymphocytic leukemia cell lines compared to B lymphocytes." (PMID 28640256, 2017). "Similarly, dinaciclib is a highly potent CDK inhibitor with selectivity for CDK1, CDK2, CDK5, and CDK9 in phase III clinical trials for the treatment of refractory chronic lymphocytic leukemia." (PMID 32412527, 2020).
Intellectual disability (4 papers, 2015 to 2024). "Mutations in cyclin-dependent kinase 5 (Cdk5) have been reported in patients with non-syndromic intellectual disability." (PMID 38542432, 2024). "Decreased CDK5 activity has been associated with intellectual disability in NF1 microdeletion syndrome patients and schizophrenia." (PMID 28077789, 2017). "While CDK5 overexpression and aberrant activation are associated with neurodegenerative diseases, a loss or reduction in CDK5 activity is implicated in certain intellectual disabilities and neurodevelopmental disorders." (PMID 28077789, 2017). "Disruption of the CDK5 or p35 (CDK5R1) genes induces abnormal neuronal layering in various regions of the mouse brain via impaired neuronal migration, which may be relevant for mental retardation in humans." (PMID 26469698, 2015).
lymphoma (4 papers, 2015 to 2023). A malignant (clonal) proliferation of B- lymphocytes or T- lymphocytes which involves the lymph nodes, bone marrow and/or extranodal sites. "In order to investigate the molecular pathways involved in the regulation of proliferation and apoptosis driven by CDK5, we measured the expression of STAT3-specific targets in lymphoma cells expressing CDK5-specific shRNAs." (PMID 28640256, 2017). "A high RIS score was also reported for the positive regulation of the reactive oxygen species (ROS) metabolic process pathway (GO:2000379) associated with the DB cell line (lymphoma) when administered with Dinaciclib (an inhibitor of CDK1, CDK2, CDK5, and CDK9)." (PMID 37432499, 2023).
mantle cell lymphoma (4 papers, 2015 to 2020). Mantle cell lymphoma is a rare form of malignant non-Hodgkin lymphoma affecting B lymphocytes in the lymph nodes in a region called the ``mantle zone''. "Decreased methylation of the cdk5 promoter region, which resulted in increased cdk5 expression, was also observed in mantle cell lymphoma." (PMID 25625291, 2015). "CDK5 hypomethylation has been described in mantle cell lymphoma." (PMID 30908498, 2019). "This particular modulation of CDK5 in DLBCL cells might depend by epigenetic modifications; indeed, in a previous study, Leshchenko and colleagues demonstrated that CDK5 is one of the most hypomethylated genes in mantle cell lymphoma." (PMID 28640256, 2017).
retinal degeneration (4 papers, 2014 to 2023). Degeneration of the retina. "Ablation of CHOP, selective activation of ATF6 or PERK, disruption of CDK5 and MEKK1 pathway, or the stimulation of ERAD may serve as a powerful therapeutic strategy against rhodopsin mutants induced RP and reverse severe retinal degeneration." (PMID 25530840, 2014).
status epilepticus (4 papers, 2009 to 2024). Status epilepticus is defined as a continuous seizure lasting more than 30 min, or two or more seizures without full recovery of consciousness between any of them. "Following status epilepticus (SE), CDK5 Y15 phosphorylation and mitochondrial fission were augmented in PV neurons." (PMID 39349423, 2024). "In status epilepticus, Cdk5 promotes neuronal apoptosis through excessive mitochondrial fragmentation, regulates neuroinflammation, and endoplasmic reticulum stress." (PMID 35966199, 2022). "Roscovitine, a Cdk5 inhibitor, inhibits status epilepticus-induced neuroinflammation by regulating p38 MAPK-mediated microglial response." (PMID 35966199, 2022). "In this study we show that chemically-induced status epilepticus and electroconvulsive shock in healthy animals induced acute generation of a Cdk5-activating cofactor, p25." (PMID 19529798, 2009). "After status epilepticus, Cdk5 was less expressed in CA1 cells in animal models." (PMID 35966199, 2022).
astrocytoma (3 papers, 2012 to 2015). "Although earlier studies have reported that knockdown of nestin by siRNA effectively reduces the proliferation and growth of C6 astrocytoma cells and its downregulation activates CdK5/p35-dependent apoptotic pathways, the precise role of nestin in tumor metastasis is obscure at present." (PMID 24498263, 2014).
autism (3 papers, 2016 to 2025). Persistent deficits in social interaction and communication and interaction as well as a markedly restricted repertoire of activity and interest as well as repetitive patterns of behavior. "Valproic acid, prenatal exposure to which causes autism-like behavioral abnormalities and brain malformation in animal models including zebrafish, downregulates Cdk5 activity in cultured mouse neurons." (PMID 38542432, 2024). "Cdk5 has been implicated in the pathogenesis of various neurological disorders including autism." (PMID 38542432, 2024). "The effects of the downregulation of Cdk5 activity on specific neuron development (a specific neuronal phenotype) can help unravel cellular and molecular mechanisms behind autism-like symptoms in animal models with follow-up studies." (PMID 38542432, 2024).
bladder cancer (3 papers, 2016 to 2025). "Research has shown that melatonin can inhibit the proliferation of bladder cancer cells and promote their apoptosis by suppressing the O-GlcNAcylation of cyclin-dependent-like kinase 5 (CDK5) and reducing the expression level of CDK5." (PMID 41059334, 2025). "The normal bladder mucosal epithelial cell line SVHUC1 and bladder cancer cell lines (T24, UMUC3) were used to determine the efficiency and specificity of CRISPR-CasΦ driven by NSGEP on knocking down CDK5 expression in bladder cancer cells." (PMID 38724931, 2024).
cerebral infarction (3 papers, 2014 to 2022). An ischemic condition of the brain, producing a persistent focal neurological deficit in the area of distribution of the cerebral arteries. "In addition, Tat-CDK5-CTM increases the CMA degradation of CDK5, reducing the infarction area and neuronal loss and improving the neurological functions in a mouse model of cerebral infarction." (PMID 35406769, 2022). "We found that Tat-CDK5-CTM at a single dose of 1 mg/kg decreased the cerebral infarction from 19.6±2.3 mm3 (vehicle) and 20.7±2.6 mm3 (Tat-s-CDK5-CTM) to 9.7±1.2 mm3." (PMID 31595208, 2019). "The MRI results showed that the Tat-CDK5-CTM treatment effectively decreased the area of cerebral infarction in all slices." (PMID 31595208, 2019). "In addition, Tat-CDK5-CTM also reduced the infarction area and neuronal loss and improved the neurological functions in a cerebral infarction mouse model." (PMID 35406769, 2022).
colorectal tumors (3 papers, 2018 to 2022). "These clinical results are consistent with our findings that CDK1/4 are highly expressed in colorectal tumor tissues and correlated with pathological stage, while CDK5 overexpression is associated with shorter OS." (PMID 35814446, 2022). "Cdk5 was detected by immunohistochemistry (IHC) in primary colorectal tumors from cohort D and scored as either negative or positive (weak and strong staining)." (PMID 31614664, 2019).
glaucoma (3 papers, 2012 to 2021). Increased pressure in the eyeball due to obstruction of the outflow of aqueous humor. "Our inability to detect P25 on day 3 after the ONC is consistent with previous reports that showed the neuroprotective effects of Cdk5 inhibition on RGCs from optic nerve transection and experimental glaucoma in rats." (PMID 34360858, 2021). "Our previous work found that Cdk5/p35 signaling pathway was activated in a rat experimental glaucoma model, and the activated Cdk5/p35 signaling in turn induced an elevation of p-NR2AS1232 expression, which contributed to rat RGC apoptotic death." (PMID 24175101, 2013). "Cdk5 is involved in ischemic hippocampal CA1 cell death and RGC apoptotic death in glaucoma rats." (PMID 22870316, 2012). "Specifically, elevated phosphorylation of the NMDAR subunit NR2A at Ser1232 (p-NR2AS1232) by Cdk5/p35 may contribute to ischemic rat hippocampal CA1 neuron death and to RGC apoptotic death in a rat experimental glaucoma model." (PMID 22870316, 2012).
metastatic tumor (3 papers, 2016 to 2025). "Our findings also suggest that Cdk5 could help decide which patients should receive adjuvant therapy and whether oxaliplatin or irinotecan should be used in the treatment of metastatic disease." (PMID 31614664, 2019). "Tumor cells formed by knocking down of CDK5 cells showed weaker metastatic ability and formed less tumors in the lungs, while tumors cells formed by CDK5-overexpressing cells were more invasive to form metastatic tumors in the lungs of nude mice." (PMID 27735944, 2016).
mood disorder (3 papers, 2014 to 2024). A cognitive disorder a disturbance in which the person's mood is hypothesized to be the main underlying feature. "Interestingly, PIF was found to have significant associations with pathways relating to mood disorders and stress, TGFβ, WNT, CDK5, and BMP." (PMID 26085845, 2014).
Neurofibrillary tangles (3 papers, 2021 to 2023). Pathological protein aggregates formed by hyperphosphorylation of a microtubule-associated protein known as tau, causing it to aggregate in an insoluble form. "REST directly targets and represses genes that mediate phospho-tau accumulation in 3xTg mice, including the tau kinases GSK3β and CDK5 which have been implicated in neurofibrillary tangle formation." (PMID 37919281, 2023). "The Cdk5/p25 is suggested to hyperactivate Cdk5 leading to tau hyperphosphorylation, a precondition for neurofibrillary tangle (NFT) formation." (PMID 37446262, 2023).
neurotoxicity (3 papers, 2012 to 2018). Toxicity that causes injury to the central or peripheral nervous system or damages its function. "Neurotoxicity deregulates Cdk5 activity either through generating a more stable proteolytic product of p35, p25, or by stabilizing Cdk5/p25 complex." (PMID 24662752, 2014).
non-small cell lung carcinoma (3 papers, 2016 to 2020). A group of at least three distinct histological types of lung cancer, including non-small cell squamous cell carcinoma, adenocarcinoma, and large cell carcinoma. "In case of pancreatic ductal adenocarcinomas and non-small lung cell cancers, increased CDK5 expression was attributed to the amplification of the CDK5 gene." (PMID 31910742, 2020). "In two subgroups of non-small cell lung cancer (NSCLC) and small cell lung cancer (SCLC), the expression of CDK5 was also higher than that of normal lung tissue, respectively (P = 0.001 and P = 0.004)." (PMID 26860827, 2016).
pancreatic ductal adenocarcinoma (3 papers, 2020 to 2021). An infiltrating adenocarcinoma that arises from the epithelial cells of the pancreas. "Cdk5 has also been suggested to play a role in growth and migration of pancreatic ductal adenocarcinoma (PDAC)." (PMID 34862365, 2021). "The marked overexpression of cyclin‐dependent kinase 5 (CDK5) or Notch1 receptor, which plays critical roles in pancreatic ductal adenocarcinoma (PDAC) development, has been detected in numerous PDAC cell lines and tissues." (PMID 33960694, 2021).
prostate tumor (3 papers, 2014 to 2019). "AR activation by CDK5 phosphorylation has been identified as a cancer-driving mechanism in prostate tumors." (PMID 26509276, 2015).
renal fibrosis (3 papers, 2016 to 2022). A final common manifestation of a wide variety of chronic kidney diseases characterized by glomerulosclerosis and tubulointerstitial fibrosis. "In diabetic rats, CDK5 inhibitor roscovitine decreased renal fibrosis and improved renal function as demonstrated by a decrease in levels of blood urine nitrogen (BUN), serum creatinine and β2-microglobulin." (PMID 27145370, 2016). "Inhibition of CDK5 reduces renal fibrosis and dedifferentiation in CKD." (PMID 36453545, 2022). "Tubule-specific deletion of CDK5 inhibits renal fibrosis and dedifferentiation in CKD." (PMID 36453545, 2022). "Thus, while data from this model suggest CDK5 is involved in the development and progression of renal fibrosis, it does not rule out potential consequences of developmental CDK5 deletion or identify the specific nephron segment where CDK5 induces a profibrotic response." (PMID 36453545, 2022).
Sepsis (3 papers, 2021 to 2022). Sepsis is defined as life-threatening organ dysfunction caused by a dysregulated host response to infection. "Our data therefore supports the approach of treating inflammatory diseases, in particular sepsis and acute lung injury, with roscovitine or other drugs that inhibit Cdk5." (PMID 34502552, 2021).
transient cerebral ischemia (3 papers, 2010 to 2020). "It has been shown that (R)-roscovitine reduced hyperphosporylation of the Tau protein, a major CDK5 target, after transient cerebral ischemia in rat, mainly by inhibiting CDK5." (PMID 20711428, 2010). "During the death of neurons in the CA1 region of the hippocampus after transient cerebral ischemia in the gerbil, hyperphosphorylation of serine 199/202 tau protein was regulated by GSK3, MAP kinase and CDK5 activity." (PMID 32019137, 2020). "The objective of this study was to determine how Cdk5 and related molecules could affect neuroprotection in the hippocampus of gerbils after with IPC [a 2-min transient cerebral ischemia (TCI)] followed by 5-min subsequent TCI." (PMID 31506563, 2019).
acute myocardial infarction (2 papers, 2021 to 2024). Necrosis of the myocardium, as a result of interruption of the blood supply to the area. "At present, the mechanisms linking circadian rhythm stabilization and myocardial infarction are under investigation and could involve inflammation, glycolysis metabolism, cyclin-dependent kinase 5, or adenosine." (PMID 34659637, 2021).
adenosquamous carcinoma (2 papers, 2016). A carcinoma composed of malignant glandular cells and malignant squamous cells. "In advanced TNM stage, CDK5 expression (90.0 %) was higher than early TNM stage (45.8 %) in adenosquamous carcinoma (P = 0.019)." (PMID 27406233, 2016). "The positive rates of CDK5 were 27.8, 31.0, 50, 54.0, 58.8, 62.7 % in chronic cervicitis, CA, carcinoma in situ, adenocarcinoma, adenosquamous carcinoma and SCC, respectively." (PMID 27406233, 2016). "The positive rates of CDK5 were 27.8, 31.0, 50, 54.0, 58.8, and 62.7 % in chronic cervicitis, CA, carcinoma in situ, adenocarcinoma, adenosquamous carcinoma and SCC, respectively." (PMID 27406233, 2016). "TNM stage was positively interrelated to CDK5 (P = 0.019) in adenosquamous carcinoma." (PMID 27406233, 2016). "CDK5 was positively interrelated to TNM stage (P = 0.017) in adenosquamous carcinoma." (PMID 27406233, 2016). "Higher CDK5-positive expression was also found in the subgroups of NSCLCs including adenocarcinoma (P = 0.003), squamous cell carcinoma (P = 0.003), adenosquamous carcinoma (P = 0.001), and undifferentiated carcinoma (P = 0.02), than that in the normal lung tissue." (PMID 26860827, 2016).